FBLN2 (fibulin 2)
Description:
Its binding to fibronectin and some other ligands is calcium dependent. May act as an adapter that mediates the interaction between FBN1 and ELN.
Tractability: Antibody: its Gene Ontology location is reachable by antibodies, with high confidence; UniProt places it where antibodies can reach, with medium confidence; UniProt predicts a signal peptide or a membrane-spanning region; the Human Protein Atlas places it where antibodies can reach.
Gene: Protein-coding gene on chromosome 3 (13,549,073 to 13,638,422, forward strand). Ensembl gene ENSG00000163520.
Subcellular location: Secreted, extracellular space, extracellular matrix
Subcellular location (Human Protein Atlas): Plasma membrane; Predicted to be secreted
Pathways (Reactome):
Extracellular matrix organization: Molecules associated with elastic fibres
Gene Ontology:
Molecular function: protein binding; calcium ion binding; extracellular matrix binding; extracellular matrix constituent conferring elasticity; extracellular matrix structural constituent
Biological process: positive regulation of cell-substrate adhesion
Cellular component: extracellular matrix; extracellular region; extracellular vesicle; elastic fiber; microfibril; non-collagenous component of interstitial matrix
Genetic constraint (gnomAD): Loss-of-function variants: 80 observed, 103.09 expected, observed/expected ratio (o/e) 0.78, 90% interval 0.65 to 0.94. The upper end of that interval is the gene's LOEUF score, 0.94, which puts it in group 3 of 6, group 1 being the genes least tolerant of losing a copy. Missense variants: 1,602 observed, 1,608.2 expected, observed/expected ratio (o/e) 1, 90% interval 0.95 to 1.04. Synonymous variants: 699 observed, 671.52 expected, observed/expected ratio (o/e) 1.04, 90% interval 0.98 to 1.11.
Gene-disease validity (ClinGen):
ClinGen rates the evidence that FBLN2 causes each of these diseases.
congenital heart disease (autosomal dominant): Limited. A heart disease that is present at birth.
pulmonary arterial hypertension (autosomal dominant): Limited. Pulmonary arterial hypertension (PAH) is a group of diseases characterized by mean pulmonary artery pressure >20 mmHg and elevated pulmonary arterial resistance leading to right heart failure.
Homologues: Orthologues: chimpanzee FBLN2 (99% identical), macaque FBLN2 (97% identical), dog FBLN2 (85% identical), rabbit FBLN2 (85% identical), pig FBLN2 (83% identical), mouse Fbln2 (82% identical), rat Fbln2 (82% identical), guinea pig FBLN2 (76% identical), zebrafish fbln2 (45% identical), tropical clawed frog fbln2 (39% identical). Paralogues in human: FBLN1 (25% identical), EYS (17% identical), VWDE (14% identical), EFEMP2 (14% identical), EFEMP1 (12% identical), FBLN5 (12% identical).
Diseases named in the same sentence as FBLN2 in open-access papers:
FBLN2 is named in the same sentence as 112 diseases in open-access papers, as found by Europe PMC text mining. Sharing a sentence is not in itself a finding about the gene and the disease. The quoted sentences say what the papers report.
breast carcinoma (26 papers, 2008 to 2024). "We have recently reported the importance of FBLN2 in the formation of a stable BM during mammary gland morphogenesis and the gradual loss of its expression in areas of tumor invasion in human breast cancer." (PMID 39110274, 2024). "Higher expression of Fbln2 mRNA was associated with better prognosis in less advanced breast cancer and this pattern was reversed in more advanced lesions." (PMID 39110274, 2024). "A protective role of ADAMTS-12 has also been found in breast cancer through its association with fibulin-2." (PMID 33996918, 2021). "High fibulin-2 was associated with luminal breast cancer subgroups (p<0.001) and inversely with interval cancers compared with screen-detected tumours (p<0.001)." (PMID 33836007, 2021). "The loss of FBLN2 contributes to invasion in breast cancer through degradation of the architecture basement." (PMID 34769264, 2021). "In fact, cleaved fibulin-2 is associated with an increase in the invasive phenotype of breast cancer cells; in addition, this processing can modify the nature of the surrounding fibroblasts by conferring protumor properties." (PMID 31508361, 2019). "In this regard, immunostaining of breast cancer tissues samples underlines the close proximity or partial co-localization of Fibulin-2 and ADAMTS-5 in different areas of grade-III invasive ductal carcinomas." (PMID 28099917, 2017). "First, anti-tumor properties associated to fibulin-2 in breast cancer are enhanced by its interaction with ADAMTS-12, especially in MCF-7 cells." (PMID 24457941, 2014). "FBLN2 is located at 3p25.1 in a region well documented for allelic loss in renal cell carcinoma and breast cancer." (PMID 20205715, 2010). "Survival analysis of Fbln2 showed different prognosis of breast cancer at different stages of tumor development, where higher Fbln2 was associated with a better prognosis in early stages; however, low Fbln2 was associated with a better prognosis in advanced breast cancer." (PMID 39110274, 2024). "FBLN2 encodes an extracellular matrix protein, fibulin-2, which was reported to suppress the proliferation of non-small cell lung cancer and the metastasis of breast cancer." (PMID 36768989, 2023). "Based on this, we hypothesized that reduced perivascular fibulin-2 expression is associated with improved tumour cell accessibility into breast cancer vessels and other features of aggressive tumours." (PMID 33836007, 2021). "For instance, this fibulin acts as an anti-angiogenic factor in nasopharyngeal carcinoma; FBLN2, the human gene coding for fibulin-2, is found epigenetically silenced in B cell acute lymphoblastic leukemia; and loss of fibulin-2 expression facilitates tumor progression in breast cancer cells." (PMID 24457941, 2014). "Our findings indicate that methylation of EMILIN2, CIDE-A and FBLN2 are associated with positive estrogen and or progesterone receptor status, this may help in further refining breast cancers that are more likely to benefit from endocrine therapy." (PMID 20205715, 2010). "The aim of this study was to establish whether perivascular fibulin-2 expression is associated with patient prognosis in breast cancer, and to see whether this expression pattern is related to vascular invasion, stromal elastosis, molecular subtypes, and tumour detection mode." (PMID 33836007, 2021). "In this study, we aimed to confirm the association of FBLN2 with myoepithelial phenotype in mammary epithelium and further investigate the expression of FBLN2 in human breast cancer subtypes in relevance to patients’ outcomes." (PMID 39110274, 2024). "In a previous study, FBLN2 has been poorly expressed in seven human breast cancer cell lines where KRT19 (luminal marker) was highly expressed." (PMID 39110274, 2024).
breast carcinoma (continued). "Analysis of FBLN2 methylation status in METABRIC dataset showed the least methylation in basal-like breast cancer, which agrees with a recent report showing an increased metastasis and invasion with methylation of Fbln2 in breast cancer." (PMID 39110274, 2024). "In different molecular subtypes, perivascular FBLN2 has shown a preferential expression in Luminal breast cancer subtypes compared to basal and Her2 + subtypes." (PMID 39110274, 2024). "Of note, antagonistic regulation of Fibulin 2 cleavage by ADAMTS5 and ADAMTS12 has been previously reported to promote invasive behaviour in breast cancer cells, potentially through production of bioactive Fibulin 2 proteolytic products." (PMID 38791926, 2024). "Meta-analyses of human breast cancer datasets from Bioportal showed a higher expression of Fbln2 mRNA in claudin-low, LumA, and normal-like breast cancers compared to LumB, Her2 +, and Basal-like subgroups." (PMID 39110274, 2024). "We have previously reported that FBLN2 contributes to BM integrity in mouse mammary gland and human breast cancer." (PMID 39110274, 2024). "Human breast cancer mRNA data from the METABRIC and TCGA datasets from Bioportal were analyzed to assess the association of Fbln2 expression with epithelial markers, and with molecular subtypes." (PMID 39110274, 2024). "According to reports, FBLN2 has been identified to exhibit tumour suppressor properties in several cancer types, such as breast cancer, non‐small cell lung cancer, and nasopharyngeal carcinoma." (PMID 38332530, 2024). "To evaluate the prognostic potential of FBLN2 expression in breast cancer patients, we assessed the relevance of Fbln2 mRNA expression to patients’ survival status using data from the KM plotter and METABRIC." (PMID 39110274, 2024). "Retrospective analysis of a previously examined cohort of 65 human breast cancer patients revealed that FBLN2 generally had a higher expression in control regions (safety margins) compared to DCIS and IDC." (PMID 39110274, 2024). "Herein, we attempted to confirm the relevance of FBLN2 to myoepithelial phenotype in mammary epithelium and to assess its expression in molecular subtypes of human breast cancer." (PMID 39110274, 2024). "In human breast cancer, we show a positive correlation of Fbln2 mRNA with basal markers (mesenchymal and myoepithelial) and a negative correlation with luminal markers." (PMID 39110274, 2024). "Of note, Fbln2 had significant positive correlations with Fbln1 and Fbln5 in all breast cancer subtypes." (PMID 39110274, 2024). "We have further reported that FBLN2 contributes to BM integrity during mouse mammary epithelial morphogenesis and in human breast cancer." (PMID 39110274, 2024). "In breast cancer, the interaction between the fibulin-2 and ADAMTS-12 proteins promotes antitumor effects, but the absence of fibulin-2 evokes the pro-tumor effect of ADAMTS-12 in breast cancer cells." (PMID 34063320, 2021). "Stromal elastosis is related to good prognosis in breast cancer and fibulin-2 helps to stabilize elastic fibers in basement membranes." (PMID 33836007, 2021). "Promoter hypermethylation is responsible for FBLN2 silencing in breast cancer and nasopharyngeal cancer." (PMID 34769264, 2021). "Since elastosis is a positive prognostic factor in breast cancer, our data are in line with findings that fibulin-2 expression reduces cell motility as well as invasion capacities in breast cancer cell lines." (PMID 33836007, 2021). "The present study indicates a link between low perivascular fibulin-2 expression and interval breast cancer." (PMID 33836007, 2021). "Here, we examined the level of perivascular fibulin-2 expression in relation to elastosis content, vascular invasion, molecular subtypes, tumour detection mode, and patient prognosis in breast cancer." (PMID 33836007, 2021). "Our data regarding the cleavage of fibulin-2 by ADAMTS-5 strengthen the tumor-protective role of fibulin-2 in breast cancer." (PMID 31508361, 2019).
breast carcinoma (continued). "In this context, where both proteins are exogenously over-expressed, the fibulin-2/ADAMTS-12 complex not only affects the cellular properties of breast cancer cell lines but also diminishes the growth of subcutaneous tumors in mice." (PMID 31508361, 2019). "In tissue sections of 65 breast cancers FBLN2 staining was lost around malignant cells with retained staining in the neighbouring histologically normal tissue margins." (PMID 30237579, 2018). "In this study, we investigated the effect of Fbln2 KD in mouse mammary epithelial cells and further studied its expression in human breast cancer." (PMID 30237579, 2018). "Using in vitro approaches and cultured breast cancer cell lines we demonstrate that Fibulin-2 is a better substrate for ADAMTS-5 than it is for ADAMTS-4." (PMID 28099917, 2017). "Taking together, these results illustrate that Fibulin-2 can influence breast cancer cell behavior depending on the presence of aggrecanases." (PMID 28099917, 2017). "In this work we show that the aggrecanases, mainly ADAMTS-5, can cleave Fibulin-2 both in vitro and in cultured breast cancer cell lines." (PMID 28099917, 2017). "We have previously reported that ADAMTS-12 is an interacting partner of Fibulin-2 and that this interaction promotes tumor-protective effects in breast cancer cells." (PMID 28099917, 2017). "To determine clinical relevance of ADAMTS-12 and fibulin-2 in breast cancer, we performed an immunohistochemical analysis of a tissue array containing 16 samples of normal and breast cancer tissues." (PMID 24457941, 2014). "Main conclusion is that ADAMTS-12/fibulin-2 interaction potentiates anti-tumor effects in breast cancer cells." (PMID 24457941, 2014). "To examine the functional consequences of the ADAMTS-12/fibulin-2 interaction, we performed different in vitro assays using two breast cancer cell lines: the poorly invasive MCF-7 and the highly invasive MDA-MB-231." (PMID 24457941, 2014). "Kaplan-Meier curves revealed that a combined high expression of both ADAMTS12 and FBLN2 correlated with the best prognosis in breast cancer patients (Hts+Hfb) when compared to patients expressing low levels of both genes (Lts+Lfb) (p < 0.001)." (PMID 24457941, 2014). "FBLN2 is hypermethylated in breast cancer and has a tumor-suppressive role in nasopharyngeal carcinomas." (PMID 24345474, 2013). "Fibulin 2, an extracellular matrix and plasma glycoprotein, facilitates invasion and migration of breast cancer cells." (PMID 21589862, 2011). "Among them, FBLN1 and FBLN2 (fibulin 2) were found to be downregulated and acted as tumour suppressive genes in certain cancers such as prostate cancer and breast cancer." (PMID 18985039, 2008). "Similarly, the downregulation of FBLN2 leads to the migration and invasion of breast cancer cells, while the binding of FBLN2 to the β chain of the integrin receptors promotes the growth of colorectal carcinoma." (PMID 39201614, 2024). "It interacts with FBLN2 to suppress the invasiveness of breast cancer cells." (PMID 35445008, 2022). "The presence of low perivascular fibulin-2 was more often observed in non-luminal subgroups and basal-like breast cancer and was associated with adverse prognosis." (PMID 33836007, 2021). "To speculate, interval breast cancers with low perivascular fibulin-2 content may have more collagen cross-linking and collagen linearization." (PMID 33836007, 2021). "Furthermore, its expression is down-regulated in more poorly differentiated tumor tissues than that of the differentiated tumor tissues for breast cancer, suggesting the influence of fibulin-2 in breast cancer proliferation and metastasis." (PMID 34063320, 2021). "Because of this context dependence, fibulin-2 may also be of importance to metastases in breast cancer and might potentially have a different role." (PMID 33836007, 2021).
breast carcinoma (continued). "Moreover, the interaction of fibulin-2 with ADAMTS-4 and ADAMTS-5 proteins favors the progression of breast cancer through the degradation of fibulin-2." (PMID 34063320, 2021). "We therefore assessed FBLN2 expression in formalin-fixed histological sections from 65 breast cancer patients with invasive breast cancer with adjacent ductal carcinoma in situ (DCIS) as well as morphologically normal breast tissue to establish its role in disease progression to invasive cancer." (PMID 30237579, 2018). "In contrast, in the high grade breast cancer patient group (Grade III (P = 0.023; n = 458)) higher Fbln2 mRNA levels were significantly associated with a poorer outcome, and showed a statistically insignificant trend with poorer DMFS in patients with positive LN status (P = 0.14; n = 382)." (PMID 30237579, 2018). "Our in vitro results supported a role for FBLN2 in BM integrity, and we therefore hypothesised that in breast cancer FBLN2 expression would be expected to be reduced in line with progression from normal to invasive tissue." (PMID 30237579, 2018). "In this work we have compared Fibulin-2 digestion pattern generated by MMP-2 with that produced by ADAMTS-5 activity concluding that Fibulin-2 might be a substrate for both metalloproteases in breast cancer." (PMID 28099917, 2017). "Further exhaustive functional and mechanistic studies will help finding out the precise role of ADAMTS-12 and fibulin-2 in relation to tumorigenesis, including the importance of the ADAMTS-12/fibulin-2 molar ratio as an indicator of potential invasiveness of breast cancer cells." (PMID 24457941, 2014). "Altogether, these data support that ADAMTS-12 fibulin-2/ interaction hampers both invasion and migration of breast cancer cells in vitro, but also that ADAMTS-12 could exert pro-tumor effects in the absence of fibulin-2." (PMID 24457941, 2014). "However, weak or absent staining was observed in 10 out 11 (91 %) samples of grade 2 and 3 breast carcinoma for both fibulin-2 and ADAMTS-12." (PMID 24457941, 2014). "In this work we show that ADAMTS-12/fibulin-2 interaction induces anti-tumor effects in breast cancer cells and our data also suggest that combined detection of both proteins could be a good prognosis marker in breast cancer patients." (PMID 24457941, 2014). "Furthermore, a decreased expression of fibulin-2 is observed in the breast cancer cell line, and the reintroduction of the same in the cell lines decrease the invasion and motility of cancer cells, suggesting the role of fibulin-2 in inhibiting the progression of cancer." (PMID 34063320, 2021). "In contrast to a suppressive role in breast cancer, experimental studies from other organs have suggested that fibulin-2 may contribute to metastases and invasion in lung and pancreatic adenocarcinoma cell lines, suggesting organ specific properties of fibulin-2." (PMID 33836007, 2021). "We have recently shown that in breast cancer FBLN2 together with COLIV is reduced in areas of invasion compared to neighbouring morphological normal tissue, with high Fbln2 RNA levels showing significant association with better DMFS in breast cancers of low and intermediate grade in KM-Plotter." (PMID 34565423, 2021). "To investigate whether FBLN2 expression was also associated with an intact BM in the human breast, we assessed co-expression of FBLN2 and COLIV in 10 out of the 65 human breast cancer tissues and histologically normal tissue margins, which were randomly chosen." (PMID 30237579, 2018). "To elucidate whether endogenous Fibulin-2 could also be degraded by these proteases, we carried out transfections only with plasmids containing the full-length cDNA for ADAMTS-4 or ADAMTS-5 into SK-BR-3 breast cancer cells, which endogenously express Fibulin-2." (PMID 28099917, 2017). "Therefore we examined whether ADAMTS-12 and fibulin-2 could also alter the mammosphere-forming ability of breast cancer cells." (PMID 24457941, 2014).